CRP (C-reactive protein)
Diseases named in the same sentence as CRP in open-access papers (continued):
Sharing a sentence is not in itself a finding about the gene and the disease.
schizophrenia (255 papers, 2009 to 2026). A major psychotic disorder characterized by abnormalities in the perception or expression of reality. "Further prospective studies are needed to determine the CRP threshold for evaluating cardiovascular risk in schizophrenia." (PMID 41281897, 2025). "More specifically, approximately 1.28% of the total effect of neuroinflammatory-specific polygenic risk scores for schizophrenia on retinal thickness is mediated by CRP levels." (PMID 40365461, 2025). "The mediator model revealed a significant effect of neuroinflammatory-specific polygenic risk scores for schizophrenia on C-reactive protein (CRP; path A coefficient of 0.01), controlling for confounding factors." (PMID 40365461, 2025). "The elevation of pro-inflammatorybiomarkers such as IL-6, IL-1β, TNF-α, and CRP has beenassociated with cognitive decline, with this association being particularlypronounced in patients with deficit schizophrenia." (PMID 40926813, 2025). "This study explores the relationship between the genetic risk for schizophrenia and retinal thickness, demonstrating that neuroinflammatory pathways are linked to retinal thinning, with C-reactive protein partially mediating this effect." (PMID 40365461, 2025). "Our study also identified significant associations between elevated inflammatory markers (CRP OR = 1.39; IL-6 OR = 1.22) and progression to schizophrenia." (PMID 41254065, 2025). "This means that part of the negative impact of neuroinflammatory-specific polygenic risk scores for schizophrenia on the ganglion cell inner plexiform layer is mediated by increased CRP levels." (PMID 40365461, 2025). "On the other hand, Hartwig and coworkers even suspected a protective effect of CRP on the risk of schizophrenia." (PMID 40980040, 2025). "Elevated CRP levels in psychiatric patients, as seen in our study, support the growing evidence that chronic low-grade inflammation is associated with schizophrenia and bipolar disorder." (PMID 40376339, 2025). "Among patients with schizophrenia, research studies have documented a positive association between BMI and CRP levels; however, the directional relationship between these biomarkers remains elusive due to the cross-sectional nature of most of these studies." (PMID 40724779, 2025). "The key findings of our study include the causal relationship between schizophrenia and CRP and a directed relationship between CRP and the linear change rate in multiple brain regions." (PMID 38445386, 2024). "The most significant was CRP, with a causal estimate of −0.035 [−0.04 to −0.03] (α, causal effects with 95% CI) in response to schizophrenia (p value = 1.71 × 10−32), and approximately 0.1% of SNPs involved indicated horizontal pleiotropy." (PMID 38445386, 2024). "Even after isolation, patients with schizophrenia showed higher stress levels associated with increased C-reactive protein, which also serves as a marker of inflammation." (PMID 37503505, 2023). "In each of the three subtypes, we measured TBV, grey matter volumes and cortical thickness and the inflammatory markers previously associated with cognition in schizophrenia: CRP, Il-6, IL1RA and TNF alpha." (PMID 35177144, 2023). "Previous investigations were mainly focused on the association of vitamin D levels and CRP levels, as an inflammatory marker, with schizophrenia and bipolar disorder." (PMID 37803327, 2023). "In a meta-analysis of 41 studies, it was reported that IL-6 and CRP levels were consistently increased in all stages of schizophrenia, and elevated CRP was associated with more cognitive impairment." (PMID 37763110, 2023). "A meta-analysis showed that low-grade inflammation measured by an elevated blood level of C-reactive protein was a frequent denominator in the inflammatory cascade and has been linked to a high risk of schizophrenia." (PMID 36906570, 2023).
schizophrenia (continued). "A high CRP level has been also shown to be associated with a more severe course of psychosis in schizophrenia and subsequent cognitive function decline." (PMID 39944368, 2023). "There is a causal relationship between the protective effect of CRP and the increased risk of schizophrenia by sIL‐6R." (PMID 37724687, 2023). "For example, observational evidence suggests elevated C-reactive protein (CRP) in the serum of individuals with schizophrenia is associated with cortical thinning in the frontal, insula and temporal regions." (PMID 36075890, 2022). "Symptoms of schizophrenia and cognitive dysfunction are strongly associated with an increase in CRP." (PMID 35269952, 2022). "Elevated CRP and pro-inflammatory cytokine levels were also associated with cognitive dysfunction in people with schizophrenia and bipolar disorder." (PMID 35163141, 2022). "MR IVW analysis confirmed that genetically elevated CRP levels (per 1-unit difference in natural log-transformed CRP) are associated with a reduced risk of schizophrenia (β = −0.120, p = 4.14 × 10−4), with consistent results across sensitivity tests." (PMID 35459240, 2022). "Recent meta-analyses have also reported a high prevalence of elevated CRP levels in schizophrenia, and previous research indicates an association between higher CRP levels in adolescence and schizophrenia at follow-up until age 27 years." (PMID 35151465, 2022). "Elevations in plasma levels of pro-inflammatory cytokines and C-reactive protein (CRP) in patient blood have been associated with impairments in cognitive abilities and more severe psychiatric symptoms in people with schizophrenia." (PMID 35027554, 2022). "The aim of the study was to search for associations between BDNF, CRP, IL-6 and clinical symptoms, cognitive and personal performance in patients with paranoid schizophrenia." (PMID 35873262, 2022). "Observational studies have reported a higher risk of schizophrenia with higher circulatory levels of CRP in younger age29, which suggest a possible role of acquiring infections in younger age in the development of schizophrenia later in life." (PMID 35459240, 2022). "MR analysis provided evidence for a causal effect of low-grade chronic inflammation as measured by genetically predicted serum CRP on a lower risk of schizophrenia supporting findings from the previous studies." (PMID 36376304, 2022). "Through MR analysis we were able to provide evidence for a causal effect of low-grade chronic inflammation as measured by genetically elevated serum CRP on lower risk of schizophrenia and prostate cancer, and a higher risk of COPD." (PMID 35459240, 2022). "Evidence of increased C-reactive protein, dysregulation of cytokines and chemokines, elevated levels of neutrophils and autoantibodies, and microbiota dysregulation in schizophrenia have the lowest risk of bias." (PMID 35546942, 2022). "Cognitive impairments in schizophrenia are associated with neuroinflammatory markers such as CRP, S100B and neuron-specific enolase, and with lower concentrations of BDNF." (PMID 34025476, 2021). "Apart from cognitive deficits, CRP levels have been associated with a variety of psychotic symptoms and different forms of schizophrenia." (PMID 34884840, 2021). "A recent Mendelian randomisation analysis has suggested a causal relationship between CRP and both schizophrenia and bipolar affective disorder." (PMID 33831008, 2021). "In a clinical study involving 105 patients with schizophrenia, treatment of the patients with atypical antipsychotics was associated with increased levels of peripheral CRP in the patients." (PMID 34955927, 2021). "Further research is needed to explore potential mechanisms of association between CRP and schizophrenia." (PMID 33711016, 2021). "The pathophysiology of schizophrenia has been linked with chronic inflammation, which stimulate inflammatory markers like CRP and IL-6." (PMID 34465310, 2021).
schizophrenia (continued). "sIL-2Rα remained associated with schizophrenia (IVW OR=1.05; 95% C.I., 1.01-1.10), but the CRP-schizophrenia association attenuated to the null." (PMID 34280516, 2021). "Vitamin D supplementation is associated with a reduction in C-reactive protein (CRP) in the general population, while in schizophrenia, an inverse relationship between vitamin D and CRP levels was identified." (PMID 32912355, 2021). "This review aims to evaluate the role of inflammation, in general, and CRP, in particular, in the pathogenesis of schizophrenia and its potential significance in diagnostic, therapeutic, and preventative approaches towards schizophrenia and psychosis." (PMID 34884840, 2021). "For CRP, we saw evidence of association with schizophrenia only, with an odds ratio (OR) of 0.91 (95% CI: 0.84‐0.99; P = 0.03) per unit change in natural log‐transformed CRP levels." (PMID 33491305, 2021). "The putative causal association with schizophrenia is even more interesting because it suggests a protective effect of CRP on schizophrenia, while observational data had suggested an association of CRP with higher schizophrenia risk." (PMID 32978716, 2021). "It is similarly vital to further investigate CRP’s role alone, or in conjunction with other biomarkers, in predicting the conversion of high-risk individuals into those with schizophrenia." (PMID 34884840, 2021). "The CRP-schizophrenia association attenuated completely after taking into account IL-6 and sIL-2Rα in MVMR (OR=1.02; 95% C.I., 0.81-1.28)." (PMID 34280516, 2021). "Two individual studies (case-control and longitudinal birth cohort study) indicated an association between increased CRP values and elevated risk of schizophrenia." (PMID 34465310, 2021). "Nevertheless, CRP has observationally shown in both cross-sectional and longitudinal research to be associated with schizophrenia, although such findings are limited by the potential of residual confounding and reverse causality." (PMID 33711016, 2021). "Within diagnosed schizophrenia patients, CRP levels should be studied in association with the severity of symptoms, relapses, and other comorbidities." (PMID 34884840, 2021). "Although previous findings identified an association between C-reactive protein (CRP) levels, and impaired cognitive functions in patients with schizophrenia (SZ), little is currently known about the relationship between inflammation, cognition, and sex in SZ." (PMID 32994460, 2020). "Birth cohort studies using maternal biomarkers of infection and inflammation obtained from pregnant maternal serum have demonstrated associations between elevated maternal CRP and schizophrenia and ASD." (PMID 31312974, 2020). "Recent data indicate that blood CRP concentrations have been associated with high central glutamate, which correlated with symptoms of anhedonia, one of the symptoms of schizophrenia." (PMID 32256401, 2020). "Whereas they included a comprehensive array of metabolic markers and CRP, future studies should consider including other inflammatory markers, e.g. IL-6 and other cytokines, that have been consistently linked with schizophrenia risk in observational studies." (PMID 31563954, 2019). "Peripheral blood markers, such as BDNF, interleukin (IL)-10, and C-reactive protein (CRP), are associated with cognitive decline in schizophrenia." (PMID 31439071, 2019). "Other studies have reported an association between higher levels of CRP at baseline and subsequent risk for schizophrenia at follow-up." (PMID 29622048, 2019). "A study by Lin and colleagues in this issue of the International Journal of Epidemiology has applied novel MR approaches to test causality of association for schizophrenia with CRP and a range of metabolic markers." (PMID 31563954, 2019).
schizophrenia (continued). "Birth cohort studies have shown that offspring of mothers with antibodies to certain infections, including influenza, and/or elevated C-reactive protein levels during pregnancy, were at increased risk for schizophrenia, ASD, and bipolar disorder." (PMID 31316403, 2019). "A few recent studies have shown a possible association between acute agitation in schizophrenia and the inflammatory marker C-reactive protein (CRP)." (PMID 31509578, 2019). "Recent meta-analyses have reported a high prevalence of elevated CRP in schizophrenia and an association between adolescent CRP and adult schizophrenia diagnosis has been found in a recent longitudinal study." (PMID 30364161, 2018). "Some studies have shown that elevated CRP is associated with poorer cognitive performance (verbal memory, global cognition) both in patients with schizophrenia and healthy older adults." (PMID 30364161, 2018). "It should be underlined that increased CRP has been associated with social withdrawal in the general population, social withdrawal being one the prodromal symptoms of schizophrenia in adolescents." (PMID 30190688, 2018). "Inconsistently with the previous findings, a large genetic study including >25,000 SZ subjects and >30,000 controls has concluded that alleles associated with increased CRP were protective from schizophrenia with a moderate effect." (PMID 30190688, 2018). "Elevated serum levels of C-reactive protein in schizophrenia are associated with the severity of cognitive impairment but not of psychiatric symptoms." (PMID 30190688, 2018). "A recent meta-analysis of 18 studies with 1,963 patients and 3,683 non-schizophrenia controls found that a diagnosis of schizophrenia was associated with a moderate increase in blood CRP, corroborating the results of a prior meta-analysis." (PMID 30766494, 2018). "This is in contradiction with another 2016 study, which identified elevated CRP levels to confer an increased risk of schizophrenia." (PMID 28847336, 2018). "Results of regression analysis showing significant contributions of diagnostic (Dx) group (schizophrenia or control), age, sex, and C-Reactive Protein (CRP) to cortical thickness." (PMID 30364161, 2018). "These updated results of the MR analysis using the limited number of SNPs indicate a protective causal association between elevated CRP levels and schizophrenia risk." (PMID 29465083, 2018). "Baseline elevated plasma CRP was associated with a 6- to 11-fold increased risk of late- and very-late-onset schizophrenia in the general population." (PMID 30190688, 2018). "Elevated CRP has been associated with impaired cognitive functioning in chronically ill patients with schizophrenia and with acute psychotic episodes." (PMID 30364161, 2018). "Our findings support the notion that lower CRP levels and blockade of IL-6 cell signaling—both associated with lower inflammation and acute phase response—increase schizophrenia risk." (PMID 29094161, 2017). "Since elevated CRP levels are in correlation with an increased risk of metabolic syndrome in schizophrenia, there is an unmet need for researchers to control their results for possible confounding factors such as body mass index (BMI), gender or smoking." (PMID 28358316, 2017). "In the total sample, evidence for an association between CRP and schizophrenia remained after adjusting for sex." (PMID 27622678, 2017). "Elevated blood levels of CRP have been observed in schizophrenia, and elevated CRP in adolescence has been associated with subsequent development of schizophrenia in adulthood." (PMID 29404313, 2017). "A longitudinal study from Denmark has reported an increased risk of late- or very-late-onset schizophrenia at follow-up for higher serum CRP levels at baseline." (PMID 27622678, 2017). "Interpreting the magnitude of estimates for the effect of CRP and IL-6 on schizophrenia risk, as well as for the mediated effect of IL-6 by circulating CRP, requires caution." (PMID 29094161, 2017).
schizophrenia (continued). "C-reactive protein (CRP) has been indicated to be associated with the pathogenesis of schizophrenia (SZ) and other psychiatric disorders." (PMID 29088880, 2017). "Evidence for an association with CRP remained after excluding participants who developed schizophrenia within a year of CRP measurement." (PMID 27622678, 2017). "Recently population-based longitudinal studies have shown that elevated IL-6 and CRP levels in childhood or adolescence are associated with increased risk of developing psychotic symptoms and schizophrenia subsequently in adulthood." (PMID 28418288, 2017). "Under mendelian randomization assumptions, our findings suggest a protective effect of CRP and a risk-increasing effect of sIL-6R (potentially mediated at least in part by CRP) on schizophrenia risk." (PMID 29094161, 2017). "Mendelian randomization has been used to investigate the effect of circulating CRP levels on schizophrenia risk." (PMID 29094161, 2017). "In schizophrenia, both CRP and Framingham risk have been linked to higher body mass index (BMI), psychiatric symptom severity, and other dysregulated metabolic factors including fasting glucose and hemoglobin A1c levels." (PMID 28396623, 2017). "The estimated proportion of the effect of inhibiting IL-6 classic signaling on schizophrenia risk that is mediated by CRP (using the IVW estimate from the liberal CRP set as the effect estimate of CRP on schizophrenia risk) was 43.8% (95% CI, 3.3% to 84.2%)." (PMID 29094161, 2017). "There was some indication that higher CRP was associated with earlier onset of schizophrenia (rs = −0.40; P = 0.07)." (PMID 27622678, 2017). "Further analyses comparing (a) schizophrenia against (b) non-schizophrenia non-affective psychosis yielded similar results to the original analyses, i.e. higher CRP at baseline was associated with increased risk of schizophrenia at follow-up." (PMID 27622678, 2017). "There was also some evidence that higher adolescent CRP levels were associated with earlier age of onset for schizophrenia." (PMID 27622678, 2017). "CRP GRSGWAS showed a statistically significant protective relationship of a 10% genetically elevated CRP level with the risk of schizophrenia (odds ratio [OR] 0.86 [95% CI 0.79–0.94]; p < 0.001)." (PMID 27327646, 2016). "GRSGWAS showed a statistically significant protective effect of lnCRP on the risk of schizophrenia (per 10-s% increase in CRP level, OR 0.86 [95% CI 0.79–0.94]; p < 0.0010)." (PMID 27327646, 2016). "The significant causal protective role of CRP for schizophrenia was consistent in both IVs using summary statistics, i.e., GRSCRP and GRSGWAS." (PMID 27327646, 2016). "We performed an in silico pathway analysis (see Discussion) to provide insights into the possible mechanism underlying the observed association of CRP level with schizophrenia." (PMID 27327646, 2016). "Given that clinical studies report elevated CRP levels in schizophrenia, one would expect to find that alleles for elevated CRP would confer an increased risk for schizophrenia." (PMID 27327646, 2016). "When only the schizophrenia subgroup (N = 36) was included, the inverse association between CRP levels and overall cognitive performance was markedly increased ((B = −1.031; Beta = -0.529; p = 0.006)." (PMID 26973142, 2016). "The exact mechanism for how elevated CRP levels are linked to schizophrenia requires a well-defined experimental analysis." (PMID 27327646, 2016). "Genetically elevated CRP levels showed a significant potentially protective causal relationship with risk of schizophrenia." (PMID 27327646, 2016). "All of the clinical features that are associated with an elevated CRP level in schizophrenia are known to be associated with impaired QoL." (PMID 26041435, 2015). "C-reactive protein has been found at increased levels in serum from schizophrenia patients and this was associated with the severity of cognitive impairment." (PMID 23118852, 2012).